PRUNE1 (prune exopolyphosphatase 1)
Description:
Exopolyphosphatase that catalyzes the hydrolysis of inorganic polyphosphates, with preference for short-chain substrates, as well as nucleoside 5'-tetraphosphates, releasing terminal phosphate residues. Also exhibits phosphodiesterase activity toward cyclic nucleotides, hydrolyzing cAMP and cGMP to their corresponding 5'-monophosphates. Requires divalent metal ions for activity. Plays a role in cell proliferation, migration and differentiation, and acts as a negative regulator of NME1. Plays a role in the regulation of neurogenesis. Involved in the regulation of microtubule polymerization.
Synonyms: DRES-17; DRES17; PRUNE; HTCD37; H-PRUNE; NMIHBA
Tractability: Small molecule: a high-quality ligand is known. PROTAC: ubiquitination databases record sites on it; a small molecule that binds it is known.
Target class: Enzyme
Gene: Protein-coding gene on chromosome 1 (151,008,420 to 151,035,713, forward strand). Ensembl gene ENSG00000143363.
Subcellular location: Cytoplasm; Nucleus; Cell junction, focal adhesion
Subcellular location (Human Protein Atlas): Cytosol
Gene Ontology:
Molecular function: phosphatase activity; protein binding; tubulin binding; exopolyphosphatase activity; 3',5'-cyclic-AMP phosphodiesterase activity; 3',5'-cyclic-GMP phosphodiesterase activity; adenosine-tetraphosphatase activity; inorganic triphosphate phosphatase activity; pyrophosphatase activity
Biological process: regulation of microtubule polymerization; regulation of neurogenesis
Cellular component: cytosol; cytoplasm; focal adhesion; nucleus
Genetic constraint (gnomAD): Loss-of-function variants: 21 observed, 33.54 expected, observed/expected ratio (o/e) 0.63, 90% interval 0.44 to 0.9. The upper end of that interval is the gene's LOEUF score, 0.9, which puts it in group 3 of 6, group 1 being the genes least tolerant of losing a copy. Missense variants: 359 observed, 459.02 expected, observed/expected ratio (o/e) 0.78, 90% interval 0.72 to 0.85. Synonymous variants: 172 observed, 189.56 expected, observed/expected ratio (o/e) 0.91, 90% interval 0.8 to 1.03.
Homologues: Orthologues: chimpanzee PRUNE1 (99% identical), macaque PRUNE1 (98% identical), pig PRUNE1 (91% identical), dog PRUNE1 (89% identical), rabbit PRUNE1 (88% identical), mouse Prune1 (85% identical), rat Prune1 (85% identical), guinea pig PRUNE1 (85% identical), tropical clawed frog prune1 (51% identical), zebrafish prune (47% identical), Drosophila melanogaster pn (28% identical).
Diseases named in the same sentence as PRUNE1 in open-access papers:
PRUNE1 is named in the same sentence as 24 diseases in open-access papers, as found by Europe PMC text mining. Sharing a sentence is not in itself a finding about the gene and the disease. The quoted sentences say what the papers report.
microcephaly (6 papers, 2017 to 2025). A congenital or acquired developmental disorder in which the circumference of the head is smaller than normal for the person's age and sex. "Biallelic pathogenic variants in PRUNE1 have been known to cause neurodevelopmental disorder with microcephaly, hypotonia, and brain abnormalities." (PMID 41300846, 2025). "Autosomal recessive pathogenic variants of PRUNE1 have been associated with microcephaly, hypotonia, and variable brain anomalies (NMIHBA, MIM #617481)." (PMID 38178891, 2023). "Recently, biallelic PRUNE1 variants have been identified in patients with neurodevelopmental disorders, hypotonia, microcephaly, variable cerebral anomalies, and other features." (PMID 38178891, 2023). "Homozygous or compound heterozygous PRUNE1 mutations cause a neurodevelopmental disorder with microcephaly, hypotonia, and variable brain malformations (NMIHBA) (OMIM #617481)." (PMID 35379233, 2022). "Recently, Karaca and colleagues identified biallelic mutations in PRUNE1 as a candidate genetic cause of microcephaly, cortical atrophy, thin or hypoplastic corpus callosum, cerebellar atrophy and global developmental delay in five affected individuals." (PMID 28334956, 2017). "PRUNE1 could also be critical for postnatal development of the nervous system as it was found to be mutated in patients with microcephaly, brain malformations, and neurodegeneration." (PMID 36831191, 2023). "We suggest that clinicians should consider the PRUNE1 gene in the diagnostic workup of any child presenting with dysmorphic features, developmental delay, microcephaly, central hypotonia, peripheral spasticity, delayed myelination, cerebral atrophy, and thin corpus callosum." (PMID 38178891, 2023). "PRUNE1 could also be required for postnatal development of the nervous system as indicated by human genetic studies, which led to the identification of several homozygous and compound heterozygous mutations of this gene in patients with microcephaly, brain malformations, and neurodegeneration." (PMID 36831191, 2023). "Similar to over case, in another study, a patient with a homozygous (c.540T>A; p.Cys180*) PRUNE1 variant has been reported who did not exhibit progressive microcephaly." (PMID 35379233, 2022).
breast carcinoma (3 papers, 2012 to 2020). "In previous studies, we demonstrated that silencing of the human PRUNE1 gene in lung and breast cancer inhibits metastasis formation and cellular migration." (PMID 28334956, 2017).
metastatic cancer (2 papers, 2012 to 2023). A carcinoma which has spread from the original site of growth to another anatomic site. "Over the years, several studies have investigated the molecular mechanisms associated with PRUNE1 overexpression in several metastatic cancers." (PMID 38178891, 2023).
brain malformations (1 paper, 2023). "In four families, potentially deleterious variants of the PRUNE1 gene, associated with intellectual disability, brain malformations, and cortical dysplasia, were identified." (PMID 38178891, 2023).
cancer (6 papers, 2014 to 2024). A tumor composed of atypical neoplastic, often pleomorphic cells that invade other tissues. "It has been observed that mutations in PRUNE1 lead to a gain of phosphodiesterase activity, promoting metastasis, cancer aggressiveness, and proliferation." (PMID 38178891, 2023). "The current knowledge on the contributions of PRUNE1 as well as NME proteins to signaling cascades is summarized with a special regard to cancer and metastasis." (PMID 38180572, 2024). "Disrupting the interaction between NME1/2 and PRUNE1, as suggested, holds the potential to be an excellent therapeutic target for the treatment of cancer and the inhibition of metastasis dissemination." (PMID 38180572, 2024). "In particular, silencing PRUNE1 in human cancer cells impaired cell motility and metastasis formation." (PMID 38178891, 2023). "Disrupting the interaction between PRUNE1 and NME1 with a competitive permeable peptide in orthotropic xenografts inhibited primary tumor growth and cancer spread; moreover, a small molecule PRUNE1 inhibitor, AA7.1, impaired MB progression and dissemination in xenografts." (PMID 30876441, 2019).
PRUNE1 also shares sentences with these, for which no sentence is quoted: developmental delay (4 papers); neurodevelopmental disorder (4); tumor (3); colorectal cancer (2); medulloblastoma (2); autosomal recessive primary microcephaly (1); brain tumors (1); Cerebellar atrophy (1); Cerebral atrophy (1); cortical dysplasia (1); Epileptic encephalopathy (1); gastric cancer (1); infantile spasms (1); Intellectual disability (1); lung carcinoma (1); neuroblastoma (1); neurological disorders (1); non-small cell lung carcinoma (1); oesophageal cancer (1).